TFAP2A-AS2 (TFAP2A antisense RNA 2)
Synonyms: HIPSTR
Gene: Long non-coding RNA gene on chromosome 6 (10,404,456 to 10,407,928, forward strand). Ensembl gene ENSG00000285278.
Diseases named in the same sentence as TFAP2A-AS2 in open-access papers:
TFAP2A-AS2 is named in the same sentence as 4 diseases in open-access papers, as found by Europe PMC text mining. Sharing a sentence is not in itself a finding about the gene and the disease.
TFAP2A-AS2 shares sentences with these, for which no sentence is quoted: carcinoma (1 paper); embryonal carcinoma (1); Klinefelter syndrome (1); tumor (1).